KRT18P1 (keratin 18 pseudogene 1)
Synonyms: dJ25J6.3
Gene: Processed pseudogene on chromosome 6 (28,969,130 to 28,970,460, reverse strand). Ensembl gene ENSG00000228666.
Diseases named in the same sentence as KRT18P1 in open-access papers:
KRT18P1 is named in the same sentence as 1 disease in open-access papers, as found by Europe PMC text mining. Sharing a sentence is not in itself a finding about the gene and the disease.
KRT18P1 shares sentences with these, for which no sentence is quoted: mental disorder (1 paper).